LINC01151 (long independently transcribed non-coding RNA 1151)
Gene: Long non-coding RNA gene on chromosome 8 (122,485,194 to 122,733,804, reverse strand). Ensembl gene ENSG00000253819.
Gene Ontology:
Biological process: miRNA-mediated post-transcriptional gene silencing; RNA processing
Cellular component: nucleolus